AOC1 (amine oxidase copper containing 1)
Diseases named in the same sentence as AOC1 in open-access papers (continued):
Sharing a sentence is not in itself a finding about the gene and the disease.
ischemic stroke (2 papers, 2021 to 2022). A stroke disorder caused by obstruction of blood flow to the brain, due to thrombotic (local blood clot formation) or embolic (due to a blood clot or other material traveling from another site) event. "In the gene sets related to overall stroke or ischemic stroke in our study, we identified ABP1, also known as AOC1 (amine oxidase copper containing 1), which has been associated with HDL, TG, and BMI." (PMID 34167563, 2021).
lactose intolerance (2 papers, 2023 to 2025). "Accordingly, in subjects with lactose intolerance, an assessment of SNPs of the AOC1 gene would be relevant to ascertain a genetic background of DAO enzyme deficiency underlying histamine intolerance." (PMID 40004469, 2025).
preeclampsia (2 papers, 2021 to 2023). Preeclampsia is a hypertensive disorder of pregnancy that is characterized by new-onset hypertension with proteinuria presenting after 20 weeks of gestation, and depending on mild or severe forms may initially present with severe headache, visual disturbances, and hyperreflexia. "Blood pressure and 24-h proteinuria of patients with preeclampsia (PE) were measured as well as the levels of miR-424-5p and amine oxidase copper containing 1 (AOC1) in placental tissues." (PMID 36788514, 2023). "Low AOC-1 activity and balance between histamine and AOC-1 is implicated in high risk pregnancies and preeclampsia." (PMID 33969702, 2021).
colon adenocarcinoma (1 paper, 2021). "First, we found AOC1 was highly expression in tumor tissues both in Colon adenocarcinoma (COAD) and Rectum adenocarcinoma (READ), according to Gene Expression Profiling Interactive Analysis (GEPIA) database." (PMID 34026633, 2021).
keratoconus (1 paper, 2020). A degenerative, structural disorder of the eye, characterized by a cone-shaped protrusion of the cornea. "In addition, a combination of genes significantly upregulated in the KJ samples only, S100A8, S100A9, ADAMTS14, LYPD2 and AOC1 may yield distinguishing biomarkers for subtypes of keratoconus." (PMID 32555404, 2020).
legionellosis (1 paper, 2021). Any disease caused by Legionella bacteria. "Interfering a series of human diseases pathways including legionellosis, toxoplasmosis, and measles and some key factors such as MAFF, HSPA1A, HSPA1B, AOC1, and MX2, high doses of moxa smoke influenced the function of rat lungs." (PMID 34961819, 2021).
liver cancer (1 paper, 2025). An epithelial or non-epithelial malignant neoplasm that arises from the liver. "In our study, AOC1 abolished sh-TFAP2A-regulated inhibition of macrophage M2 polarization, which was consistent with the previous finding that TFAP2A could enhance M2 polarization of macrophages in liver cancer." (PMID 40813717, 2025).
lung carcinoma (1 paper, 2025). "However, the specific role of amine oxidase like AOC1 in lung cancer is still less studied." (PMID 40813717, 2025).
lymph node metastasis (1 paper, 2022). "The Gleason score, T classification, lymph node metastasis, and distant metastasis are negatively correlated with AOC1 expression according to a clinical information analysis, thus demonstrating its importance as a clinical indicator." (PMID 35922412, 2022).
metastatic prostate carcinoma (1 paper, 2022). A carcinoma that arises from the prostate gland and has spread to other anatomic sites. "TCGA database data showed that low expression of AOC1 is associated with a poor prognosis, thus confirming our hypothesis of significant ablation in metastatic prostate cancer." (PMID 35922412, 2022).
oral cancer (1 paper, 2023). "On the other hand, suggestive evidence that AOC1 expression has a negative association with oral cancer was found; however, this association was not corroborated when using DBP GWAS as an instrument." (PMID 38089045, 2023).
severe combined immunodeficiency (1 paper, 2022). Severe combined immunodeficiency (SCID) comprises a group of rare monogenic primary immunodeficiency disorders characterized by a lack of functional peripheral T lymphocytes resulting in early-onset severe respiratory infections and failure to thrive. "At the same time, 22Rv1 cells with different treatments were inoculated in severe combined immunodeficiency mice, and the results showed that AOC1 depletion could significantly accelerate tumor growth in vivo." (PMID 35922412, 2022).
somnolence (1 paper, 2018). "Additionally, a correlation was revealed between clozapine-induced somnolence and rs2737385 polymorphism on HNMT gene, rs1552498 and rs17034063 polymorphisms on HRH1 gene (Histamine Receptor H1), as well as rs697738 polymorphism on AOC1 gene (Amine Oxidase Copper Containing 1)." (PMID 29587340, 2018).
Stroke (1 paper, 2025). Sudden impairment of blood flow to a part of the brain due to occlusion or rupture of an artery to the brain. "For Stroke, there were 3,221 genes and 458 proteins, with 57 overlapping targets at the gene-protein level including ABO, AOC1, and ARL2BP." (PMID 41340073, 2025).
type 2 diabetes (1 paper, 2023). "The index variants are rs62492368 and rs7794796, both located in the intron of AOC1. rs62492368 is associated with type 2 diabetes, and rs7794796 is associated with appendicular lean mass." (PMID 37433298, 2023).
cancer (14 papers, 2019 to 2025). A tumor composed of atypical neoplastic, often pleomorphic cells that invade other tissues. "Immunohistochemical staining of AOC1 protein on adjacent cancer section were coincident with the AOC1 gene expression image." (PMID 37164975, 2023). "According to recent research studies, in order to stop the growth of cancer cells, the activity of AOC1 on spermidine produces reactive oxygen species and results in ferroptosis." (PMID 36733434, 2023). "Colony formation assays in vitro also verified that supplementing SOX15 can enhance the cancer suppression effect of AOC1." (PMID 35922412, 2022). "The results showed that the cancer-suppressing effect of spermidine was greatly reduced after knocking down AOC1, suggesting that AOC1 has an irreplaceable role in the ability of spermidine to promote ferroptosis." (PMID 35922412, 2022). "Eight genes are in the overlap of all subgroups, among them immune-related genes (DEFB1, AOC1, JCHAIN) as well as genes (215780_s_at/SET, SPP1) that were reported in the literature to be associated with different types of cancer." (PMID 34876106, 2021). "The network surrounding Il10ra shows that many of them are cancer related, e.g., Reg3g, Aoc1, Mep1a, Irf7, Gas6, B3gnt7, Tap1, Tgm2, and Nos2." (PMID 33396408, 2020). "The 13 overexpressed genes were reported to play a role in RCC: PAX2, NAT8, GBA3, SLC22A2 other cancer types: AOC1, HAO2, TMEM27, cell death (NPR3) or kidney metabolism: TMEM171, CYS1." (PMID 31150395, 2019). "AOC1, a copper-containing amine oxidase, plays different roles in different carcinomas." (PMID 37525249, 2023). "Additionally, our results showed that low concentrations of spermidine (10 μM) could achieve better anti-cancer growth effects when accompanied by AOC1 overexpression." (PMID 35922412, 2022). "In addition, AOC1 has the ability to regulate pathophysiological processes, such as cancer and EMT." (PMID 34744725, 2021).
tumor (14 papers, 2015 to 2026). "However, upregulated AOC1 expression in HCC tissues was associated with a poor prognosis in the study that used a large number of clinical samples (Tumor tissues and adjacent-normal tissues of 85 patients from the hospital) and highly aggregated data." (PMID 36313717, 2022). "Then, researchers found that AOC1 expression was noticeably higher in NSCLC metastasis tissues than in primary tumor tissues." (PMID 40813717, 2025). "Beyond that, western blot analysis exhibited that the protein levels of METTL14, AOC1, Cyclin D1, Bcl-2, and N-cadherin were clearly lower in tumor tissues derived from sh-METTL14-transfected C666-1 cells." (PMID 38956710, 2024). "The AOC1 gene regulates the oxidation of histamine and its expression is highest in tumor tissue, followed by serrated lesion and lowest in normal epithelium." (PMID 37164975, 2023). "The results showed that a total of 181 samples had tumor mutation burden (TMB), of which OGDHL gene had the highest mutation frequency, followed by AOX1 and AOC1." (PMID 36185621, 2022). "All these results suggested that spermidine supplementation was able to significantly increase the inhibitory effect of AOC1 on tumor progression." (PMID 35922412, 2022). "Because of catalyzed oxidation of diamines to aldehydes, AOC1 regulates many biological processes, such as tumor growth and development, inflammation, and neoplasm." (PMID 35922412, 2022). "Studies have shown the diverse involvement of AOC1 in allergic and immune responses, tumor formation, and tissue differentiation." (PMID 35922412, 2022). "Xenograft tumor formation in nude mice showed that knockdown of AOC1 inhibited the tumor xenografts growth in vivo." (PMID 34026633, 2021). "Firstly, we found that AOC1 was highly expression in tumor tissues both in COAD and READ, and AOC1 expression was statistically significant for predicting tumor clinical stage according to GEPIA database (p=0.0459)." (PMID 34026633, 2021). "In summary, these indicate that the upregulation of AOC1 in tumor tissues significantly correlates with worse clinical outcomes in CRC patients and is an independent prognostic factor in CRC patients after surgery." (PMID 34026633, 2021). "The results showed that AOC1 was highly expressed in the tumor epithelium, suggesting that the positive expression pattern of AOC1 was the location of the tumor epithelium cytoplasm." (PMID 34026633, 2021). "Next, the GEPIA database evaluated that AOC1 expression was statistically significant for predicting tumor clinical stage according to GEPIA database (p = 0.0459)." (PMID 34026633, 2021). "Proliferation assays (Cell Counting Kit‐8 and colony formation assays), migration assays (Transwell and wound healing assays) and xenograft tumor formation in nude mice were performed to assess the biological role of AOC1 in CRC cells." (PMID 34026633, 2021). "we tested the mRNA and protein levels of AOC1 expression in paired tumor and normal tissues by qRT-PCR and western blotting, respectively." (PMID 34026633, 2021). "Consistent with the result of the cell proliferation assay in vitro, knockdown of AOC1 significantly inhibited the tumor xenografts growth." (PMID 34026633, 2021). "Additionally, AOC1 is involved in regulating many biological processes, such as tumor growth and development, and neoplasia." (PMID 40813717, 2025). "The tumor volume was inhibited by sh-AOC1 in a time-dependent manner." (PMID 40813717, 2025). "Furthermore, with the advent of the era of organoid culture in vitro, we found that AOC1 had higher expression in tumor organoids than in normal organoids by using this advanced technology, suggesting that it was highly located in the tumor epithelium." (PMID 34026633, 2021). "In summary, these results indicated that AOC1 played an oncogenic role in promoting tumor growth." (PMID 34026633, 2021). "These indicated that AOC1 was highly expressed in the tumor tissues." (PMID 34026633, 2021).
tumor (continued). "In addition, AOC1 had higher expression in tumor organoids than in normal organoids, suggesting that it was highly expressed in the tumor epithelium." (PMID 34026633, 2021). "However, up-regulation of AOC1 promoted tumor volume and was positively related to time." (PMID 40813717, 2025). "In terms of NPC, the overexpression of AOC1 might expedite tumor cell proliferation and migration." (PMID 38956710, 2024). "However, overexpressing SOX15 will reverse the effect of AOC1 on tumor growth." (PMID 35922412, 2022). "Consistent with the result of the cell proliferation assay in vitro, AOC1-knockdown sw480 xenograft tumors were dramatically smaller than the tumors derived from control sw480 cells, suggesting that knockdown of AOC1 significantly inhibited the tumor xenografts growth." (PMID 34026633, 2021). "Similar results were obtained in western blot assay, namely, AOC1 expression was promoted in NSCLC tissues (Normal (n = 4) and Tumor (n = 4))." (PMID 40813717, 2025). "The RT-qPCR results demonstrated that AOC1 was increased in NSCLC tissues when compared with the Normal group (Normal (n = 89) and Tumor (n = 89))." (PMID 40813717, 2025). "AOC1 also activates the AKT signaling pathway and regulates the epithelial-to-mesenchymal transition (EMT) process, which promotes tumor cell proliferation and migration." (PMID 38874871, 2024). "The gene expressions of AOC1 (P < 0.001), FDX1 (P = 0.003), MT-CO1 (P < 0.001), and ACO1 (P < 0.001) in HCC tumor tissues were remarkably lower than those in normal tissues." (PMID 36313717, 2022). "To further study the mechanism through which AOC1 affects the occurrence and development of CRC, as well as promoting tumor proliferation and metastasis, we found that AOC1 regulated the migratory ability of CRC cells by EMT pathway." (PMID 34026633, 2021). "Silencing AOC1 suppressed tumor weight of NSCLC, but AOC1 increased the tumor weight of NSCLC." (PMID 40813717, 2025). "AOC1 and TFAP2A levels were increased in NSCLC tumor tissues and cell lines (A-549 and NCI-H1299)." (PMID 40813717, 2025). "The outcome that high expression of AOC1 (P = 0.007) that associated with poor survival rate in HCCs by survival analysis was not consistent with lower expression in HCC tumor tissues by differential expression analysis." (PMID 36313717, 2022). "As we had expected, AOC1 was highly expressed in tumor organoids compared to the normal one, suggesting that it was highly expressed in the tumor epithelium." (PMID 34026633, 2021).
infection (5 papers, 2013 to 2022). The state of being infected such as from the introduction of a foreign agent such as serum, vaccine, antigenic substance or organism. "Results revealed that LOX2, LOX3, and AOC1 were simultaneously highly expressed in ZmGLP1-overexpressing lines after PstDC3000 infection, indicating that ZmGLP1 may participate in plant defense mechanisms against biotrophic PstDC3000 by activating the JA-dependent signaling pathway." (PMID 36430797, 2022).
intestinal diseases (1 paper, 2024). "AOC1 gene is a marker of intestinal diseases, and its expression is higher in the old compared to the lamb stage." (PMID 38414776, 2024).
neurological disorders (1 paper, 2023). "AOC1 (ENSG00000002726.20, predicted by LASSO) and another epidemiological factor, NOS2, are the two major factors reported to be associated with the neurological disorders causing taste and smell loss, validating the efficacy and accuracy of our prediction." (PMID 36983953, 2023).
AOC1 also shares sentences with these, for which no sentence is quoted: Allergy (4 papers); Alzheimer disease (4); attention deficit-hyperactivity disorder (3); Crohn disease (3); nasopharyngeal carcinoma (3); anaphylaxis (2); Cirrhosis (2); Cognitive impairment (2); colitis (2); enteritis (2); Obesity (2); Sepsis (2); abdominal aortic aneurysm (1); acute pancreatitis (1); allergic rhinitis (1); antiquitin deficiency (1); Anxiety (1); asthma (1); atherosclerosis (1); cardiovascular disease (1); celiac disease (1); Chronic colitis (1); diabetes (1); end-stage renal disease (1); familial medullary thyroid carcinoma (1); food allergy (1); gastrointestinal disease (1); gastrointestinal disorders (1); gout (1); head and neck cancer (1).
A further 28 diseases each share a sentence with AOC1 in 1 paper.